RNU6-1331P (RNA, U6 small nuclear 1331, pseudogene)
Gene: Small nuclear RNA gene on chromosome 8 (53,914,719 to 53,914,824, forward strand). Ensembl gene ENSG00000200528.
Homologues: Orthologues: chimpanzee U6 (95% identical), macaque U6 (93% identical). Paralogues in human: RNU6-43P (91% identical), RNU6-727P (91% identical), RNU6-15P (90% identical), RNU6-189P (90% identical), RNU6-242P (90% identical), RNU6-379P (90% identical), RNU6-445P (90% identical), RNU6-66P (90% identical), RNU6-1011P (89% identical), RNU6-11P (89% identical), RNU6-1274P (89% identical), RNU6-166P (89% identical), and 1287 more.